AGO2 (argonaute RISC catalytic component 2)
Diseases named in the same sentence as AGO2 in open-access papers (continued):
Sharing a sentence is not in itself a finding about the gene and the disease.
retinal degeneration (2 papers, 2021). Degeneration of the retina. "Ago2 interruption led to a decreased threshold for miRNA-mediated retina-associated gene silencing, which caused retinal degeneration and was followed by the abnormal expression of neuronal and non-neuronal miRNAs." (PMID 34529004, 2021). "And, the retinal degeneration caused by Ago2 silencing was more serious than Ago2 overexpression." (PMID 34529004, 2021). "To understand the change in miRNA binding sites in response to retinal degenerations, we used sequence motif enrichment analysis within the 3′ UTRs of AGO2-bound mRNAs identified by HITS-CLIP." (PMID 34465369, 2021). "We thought that Ago2 interruption in our study decreased some miRNAs directly and that the dysregulation of miRNAs further led to the retinal degeneration." (PMID 34529004, 2021). "Taken together, our findings demonstrated that the silencing or overexpression of Ago2 in mice led to a severe retinal degeneration phenotype." (PMID 34529004, 2021). "Taken together, these data suggest that the silencing of Ago2 led to retinal degeneration obviously and the damage mainly occurred in the outer retina layer." (PMID 34529004, 2021). "We found that Ago2 disruption led to severe retinal degeneration, including shortened inner segment/outer segment (IS/OS), thinned outer nuclear layer (ONL), and impaired ERG response." (PMID 34529004, 2021). "The overexpression of Ago2 led to retinal degeneration similar to that of the AAV-shAgo2-EGFP–treated retina." (PMID 34529004, 2021). "Our finding demonstrated that Ago2 interruption led to severe retinal degeneration, suggested that Ago2 homeostasis contributed to retinal structural and functional maintenance." (PMID 34529004, 2021). "We hypothesized that silencing or overexpression of Ago2 in retina would result in dysregulation of miRNAs and miRNA targets, and then lead to retinal degeneration." (PMID 34529004, 2021). "OCT and immunostaining assays showed that silencing of Ago2 resulted in severe defects in the outer retina, and the inner retina thickness remained relatively normal, indicating that retinal degeneration mainly occurred in the photoreceptors first and then extended to the inner retina." (PMID 34529004, 2021). "Ago2 disruption may lead to dysregulation of genes in the retina, followed by severe retinal degeneration, especially in the photoreceptors." (PMID 34529004, 2021).
rheumatic diseases (2 papers, 2006 to 2025). "For example, anti-Su autoantibodies found in rheumatic diseases, including SLE, recognize Argonaute2 (Ago2), an miRNA catalytic enzyme." (PMID 40045202, 2025).
Stroke (2 papers, 2020). Sudden impairment of blood flow to a part of the brain due to occlusion or rupture of an artery to the brain. "In fact, stroke substantially modifies Ago2-associated miRNA profiles in the brain in a stroke rat model." (PMID 32175077, 2020).
Tinnitus (2 papers, 2021 to 2022). Tinnitus is an auditory perception that can be described as the experience of sound, in the ear or in the head, in the absence of external acoustic stimulation. "We obtained SNPs in AGO2 and TNRC6B showing association with tinnitus." (PMID 36581688, 2022). "The interplay between AGO2 and TNRC6B might influence regulatory RNA mechanisms contributing to tinnitus." (PMID 36581688, 2022).
type 1 diabetes (2 papers, 2023 to 2025). "Next, we found that the Ago2 expression significantly decreased in the penis tissues of STZ-induced type-1 diabetic mice (DM) compared with age-matched controls." (PMID 36769259, 2023).
acute promyelocytic leukemia (1 paper, 2013). An aggressive form of acute myeloid leukemia (AML), characterized by arrest of leukocyte differentiation at the promyelocyte stage, due to a specific chromosomal translocation t(15;17) in myeloid cells. "Similar results were obtained with freshly isolated AML-M3 acute promyelocytic leukemia (APL) primary blasts showing a higher Ago2 basal expression level compared with NB4 cells." (PMID 24263100, 2013). "We observed that Ago2 protein levels are increased during monocyte differentiation of myeloid progenitors, whereas Ago2 is downregulated during granulocyte differentiation of human leukemic cell lines and freshly isolated blasts from acute promyelocytic leukemia patients." (PMID 24263100, 2013).
adenovirus infections (1 paper, 2014). "To investigate in depth the small RNA production during different adenovirus infections, we sequenced the cytoplasmic (referred to as Cyto) and RISC bound (referred to as RISC-IP) small RNA pools isolated at 24 hpi from Ad4, Ad5, Ad11, and Ad37-infected 293-Flag-Ago2 cells." (PMID 25144466, 2014).
adrenal adenoma (1 paper, 2024). "AGO2 is upregulated in ACC compared to adrenal adenoma and the NAC." (PMID 39404265, 2024). "Our results demonstrated that among all miRNA processing components, AGO2 exhibited significant overexpression in ACC compared to the normal adrenal cortex and benign adrenal adenoma (P < 0.001)." (PMID 39404265, 2024).
adult T cell Leukemia (1 paper, 2023). "Interestingly, the authors measured DROSHA, DGCR8, XPO5, DICER1, AGO2, and AGO3 mRNA expression, and only DICER1 mRNA was differently expressed in CD8+ T-cell–depleted PBMCs from HTLV-1 asymptomatic carriers when compared to patients with acute adult T cell Leukemia." (PMID 37243263, 2023).
AIDS (1 paper, 2019). A syndrome resulting from the acquired deficiency of cellular immunity caused by the human immunodeficiency virus (HIV). "Interestingly, autoAbs against AGO2 have been reported in several AIDs, including primary biliary cirrhosis, anti-phospholipid syndrome, and inflammatory myositis." (PMID 31494269, 2019).
alcohol dependence (1 paper, 2023). Physical and psychological dependence on alcohol. "Moreover, Gedik reported a genetic association of DGCR8, AGO1, and AGO2 alleles with alcohol dependence risk." (PMID 38116240, 2023).
alcoholic hepatitis (1 paper, 2023). Acute hepatitis resulting from ingestion of alcohol. "Furthermore, miR-214, which is upregulated in alcoholic hepatitis, increases ferroptosis by activating ferroptosis-driver genes (ACSL4, PRKAA2, and SLC38A1) through AGO2-dependent transcriptional mechanisms." (PMID 37626043, 2023).
anemia (1 paper, 2018). A reduction in the number of red blood cells, the amount of hemoglobin, and/or the volume of packed red blood cells. "Mice deficient in Argonaut 2 (Ago2) suffer from severe anemia, which is caused by the failure of miR-144/451 to act on its targets." (PMID 30087616, 2018).
atrial fibrillation (1 paper, 2025). A disorder characterized by an electrocardiographic finding of a supraventricular arrhythmia characterized by the replacement of consistent P waves by rapid oscillations or fibrillatory waves that vary in size, shape and timing and are accompanied by an irregular ventricular response. "tsRNA-5008a modulates SLC7A11, a marker associated with ferroptosis, through AGO2 targeting, thereby increasing fibrosis and ferroptosis in myocardial tissue, which in turn exacerbates the progression of atrial fibrillation (AF)." (PMID 40001986, 2025).
autoimmune thyroid disease (1 paper, 2019). Inflammatory disease of the thyroid gland due to autoimmune responses leading to lymphocytic infiltration of the gland. "Polymorphisms and expression of the AGO1 and AGO2 genes have been associated with autoimmune thyroid diseases." (PMID 31494269, 2019).
B-cell lymphoma (1 paper, 2016). "To determine the target genes of miR-155 in B-cell lymphoma we performed Ago2-RIP-Chip following two strategies." (PMID 26497687, 2016). "To identify miR-155 target genes relevant for the pathogenesis of B-cell lymphoma we performed Ago2-immunoprecipitation in B-cell lymphomas with high and low miR-155 expression levels." (PMID 26497687, 2016).
bladder tumor (1 paper, 2018). "We obtained significant differences between AGO1/AGO2 and AGO1/Drosha expression in bladder tumor tissue samples (p < 0.001)." (PMID 29857476, 2018).
breast invasive carcinoma (1 paper, 2014). "Since the incidence of alteration of the AGO2 gene was highest in breast invasive carcinoma, we analyzed the miRNA machinery genes in breast invasive carcinoma datasets to identify patterns of mutual genetic alterations and driver genes." (PMID 24904827, 2014).
Breast Invasive Ductal Carcinoma (1 paper, 2020). "Ago2 was found to be upregulated in the Curtis Breast Invasive Ductal Carcinoma (IDC) dataset as well as both of the “The Cancer Genome Atlas” (TCGA) datasets, but no significant change was noted in the Curtis Breast Invasive Lobular Carcinoma (ILC) dataset." (PMID 32872485, 2020).
Burkitt lymphoma (1 paper, 2022). A rare form of malignant mature B-cell non-Hodgkin lymphoma. "Similarly, BGLF2-FLAG was confirmed to interact with Ago2 in Raji Burkitt’s lymphoma cells, reactivated to the lytic cycle by sodium butyrate/TPA treatment." (PMID 35007297, 2022).
CHARGE syndrome (1 paper, 2023). CHARGE syndrome is a multiple congenital anomaly syndrome characterized by the variable combination of multiple anomalies, mainly Coloboma; Choanal atresia/stenosis; Cranial nerve dysfunction; Characteristic ear anomalies (known as the major 4 C's). "Importantly, this mechanism is most likely at play in human cells as well, as evidenced by the reduced nucleus:cytoplasm ratio of AGO2 in a lymphoblastoid cell line derived from a CHARGE syndrome child bearing the FAM172A variant E228Q." (PMID 37221016, 2023). "Altogether, these data are thus in agreement with a general model suggesting that proper FAM172A-mediated nuclear import of AGO2 might be necessary to avoid developing CHARGE syndrome-associated cellular and molecular anomalies." (PMID 37221016, 2023).
cognitive decline (1 paper, 2017). "In accordance with this notion, we have previously shown in Drosophila that mutation of Ago2, a major effector protein of the siRNA system, results in activation of several different RTEs in brain tissue and causes rapid age-related cognitive decline and shortened lifespan." (PMID 28301478, 2017).
craniosynostosis (1 paper, 2021). Craniosynostosis is defined as the premature fusion of one or more cranial sutures leading to secondary distortion of skull shape resulting in skull deformities with a variable presentation. "Individual 12-I presented with a craniosynostosis that was surgically corrected at the age of 6 months, which may be explained by the patient’s additional de novo heterozygous AGO2 variant." (PMID 33941880, 2021).
depression (1 paper, 2022). "Based on the obtained results, we found that the studied patients demonstrated a lower risk of depression with the presence of the polymorphic variant of the rs4961280/AGO2 gene—genotype C/A and C/A-A/A." (PMID 36142498, 2022). "In our work, we looked for a relationship between AGO1 and AGO2 polymorphisms and the risk of depression." (PMID 36142498, 2022). "More research is needed so as to confirm that AGO2 plays a key role in the pathogenesis of depression and to provide additional evidence that the regulation of AGO2 expression or activation can be used as a tool in prevention of depression." (PMID 36142498, 2022). "We have noticed, in turn, that the rs4961280/AGO2 gene plays a protective role against depression." (PMID 36142498, 2022). "The aim of our research was to assess the relationship between the occurrence of depression and the presence of SNPs in genes AGO1 (rs636882) and AGO2 (rs4961280; rs2292779; rs2977490) in a Polish population." (PMID 36142498, 2022). "Thus, the aim of the author’s own research was to assess the relationship between the occurrence of depression and the presence of SNP in genes: AGO1 (rs636882) and AGO2 (rs4961280; rs2292779; rs2977490)." (PMID 36142498, 2022).
esophageal cancer (1 paper, 2020). A primary or metastatic malignant neoplasm involving the esophagus. "Furthermore, AGO2 knockdown increased PSMA3-AS1 expression in esophageal cancer KYSE150 and KYSE450 cells." (PMID 32005028, 2020). "The levels of PSMA3-AS1 and miR-101 were highly enriched in esophageal cancer KYSE150 and KYSE450 cells as suggested by a RIP assay using an AGO2 antibody." (PMID 32005028, 2020).
Ewing sarcoma (1 paper, 2017). A small round cell tumor that lacks morphologic, immunohistochemical, and electron microscopic evidence of neuroectodermal differentiation. "Using a combination of AGO2 pull-down experiments by PAR-CLIP (Photoactivatable-Ribonucleoside-Enhanced Crosslinking and Immunoprecipitation) and of RNAseq upon miRNA depletion by ectopic sponge expression, we aimed to identify the targetome of miR-17-92 in Ewing sarcoma." (PMID 28030800, 2017).
Fibroadenoma (1 paper, 2024). A benign tumor of the breast characterized by the presence of stromal and epithelial elements. "Compared with noncancerous breast tissues (i.e., normal breast tissues, breast tissues with hyperplasia, inflammation, or fibroadenoma, and cancer-adjacent breast tissues), the levels of plasma membrane-associated Ago2 were significantly higher in primary carcinomas (P = 2.64 × 10−10)." (PMID 38649663, 2024).
HIV-1 infection (1 paper, 2013). The type species of lentivirus and the etiologic agent of acquired immunodeficiency syndrome (AIDS). "Except Dicer, all other cytoplasmic RNAi components enhance HIV-1 replication, indicating crucial role of Dicer independent (Ago2 dependent) RNAi pathway in HIV-1 infection." (PMID 24025624, 2013). "The presented data suggest a possible role of Dicer independent (Ago2 based) RNAi in HIV-1 infection." (PMID 24025624, 2013). "To analyze the Dicer dependent and Dicer independent RNAi in HIV-1 infection, we assessed Dicer and Ago2 processed microRNA signature pattern in precursor microRNA (using miRNAMap, a structural database of miRNAs) that are known to be differentially regulated in HIV-1 infection." (PMID 24025624, 2013).
Infertility (1 paper, 2021). "Given the sensitivity to gene dosage and the essential functions of these target genes, increased miRNA-guided AGO2-mediated cleavage of their transcripts and decreased protein synthesis may contribute to the infertility of Mov10l1 CKO mutants." (PMID 34645830, 2021).
inflammatory skin disorders (1 paper, 2015). "MicroRNA-184 has also been shown to increase in response to interleukin-22 (IL-22), a proinflammatory cytokine associated with inflammatory skin disorders, thereby reducing expression of Argonaute-2 (AGO 2) protein in human keratinocytes." (PMID 25612225, 2015).
influenza infection (1 paper, 2025).
insulinoma (1 paper, 2024). "In agreement with the findings in insulinoma cells, the current study suggests the involvement of Ago-2/miR-335 RISC complex in restricting hIAPP protein expression and secretion in human islets under elevated metabolic flux evoked by high glucose." (PMID 39273561, 2024).
invasive carcinoma (1 paper, 2022). A carcinoma that is not confined to the epithelium, and has spread to the surrounding stroma. "As Ago2 is a common miRNA processing factor, increasing Ago2 levels may promote or repress tumor growth in patients with invasive carcinomas." (PMID 35459267, 2022).
kidney cancer (1 paper, 2023). Primary or metastatic malignant neoplasm involving the kidney. "The AGO2 rs4961280 AA/AC genotype is considered a biomarker of poor prognosis in RCC and the expression level of AGO2 can effectively reflect kidney cancer invasiveness." (PMID 37968670, 2023).
Lessel-Kreienkamp syndrome (1 paper, 2025). "Lessel-Kreienkamp syndrome (LESKRES, MIM #619149), an autosomal dominant genetic disorder caused by variants in AGO2 (MIM*606229), primarily leads to neurodevelopmental symptoms." (PMID 40574801, 2025).
lung diseases (1 paper, 2017). "The significant Ago2-IP enrichment of targets of these miRNAs related to the TGF-β and/or Wnt pathways (NGF, DLD, HHEX) in TGF-β1-stimulated fibroblasts suggest a role for these miRNAs in lung diseases by affecting lung fibroblast function." (PMID 28910321, 2017).
megakaryoblastic leukemia (1 paper, 2018). "Ago2 immunoprecipitation showed marked enrichment of miR-21 in a human megakaryoblastic leukemia cell line." (PMID 30385722, 2018).
ovarian cystadenoma (1 paper, 2018). A benign ovarian surface epithelial-stromal tumor characterized by the presence of cystic structures lined by serous epithelial cells, mucinous columnar epithelial cells, or endometrial-type well-differentiated cells. "Prior to quantification of exosomal miRNAs, extracted exosomes from two healthy women, one ovarian cystadenoma patient, and each two EOC patients at FIGO stage III and stage IV were verified on a western blot using antibodies specific for the exosomal marker CD63 and the miRNA binding protein AGO2." (PMID 30107086, 2018).
ovarian tumor (1 paper, 2021). "A copy number increase in Dicer1 and Ago2 loci has also been reported in, respectively, 24.8% and 51.5% of ovarian tumor regions." (PMID 34721577, 2021).
Pancreatic cysts (1 paper, 2020). A cyst of the pancreas that possess a lining of mucous epithelium. "One mouse of the AGO2fl/fl;KRASG12D;p48Cre genotype developed a pancreatic cyst (without AGO2 expression), histologically resembling the mucinous cystic neoplasm, and survived for 368 days." (PMID 32499547, 2020).
post-traumatic stress disorder (1 paper, 2022). An anxiety disorder precipitated by an experience of intense fear or horror while exposed to a traumatic (especially life-threatening) event. "A study conducted on peripheral blood mononuclear cells from post-traumatic stress disorder patients concluded that the chronic inflammation observed in these individuals could be triggered by downregulation of Ago2 and Dicer1, which impairs the generation of mature miRNA." (PMID 34991639, 2022).
preeclampsia (1 paper, 2025). Preeclampsia is a hypertensive disorder of pregnancy that is characterized by new-onset hypertension with proteinuria presenting after 20 weeks of gestation, and depending on mild or severe forms may initially present with severe headache, visual disturbances, and hyperreflexia. "This suggests another role for AGO2 in preeclampsia via IPA of VEGF-related signaling pathways." (PMID 40745234, 2025).
prostate adenocarcinoma (1 paper, 2013). "To determine if this feature is conserved in human cells, we examined Ago1 and Ago2 cellular distribution in the nuclear and cytosolic fractions of PC-3 (prostate adenocarcinoma) and RWPE-1 (normal prostatic epithelial) cells by immunoblot analysis." (PMID 24086155, 2013).
schizophrenia (1 paper, 2021). A major psychotic disorder characterized by abnormalities in the perception or expression of reality. "Traits with significant gene associations include number of children born (GLB1L2), risk-taking behavior (HFE2 and AGO2), and schizophrenia (SLTM)." (PMID 33648717, 2021).
skin cutaneous melanoma (1 paper, 2022). "AGO2 expression positively correlates with the MLL4 mRNA level in most TCGA tumor types, including skin cutaneous melanoma (SKCM), as well as in CCLE tumor-cell lines when correlative analyses were conducted using either all cell lines or cell lines grouped according to their tissue of origin." (PMID 36323669, 2022).
tongue squamous cell carcinoma (1 paper, 2021). A squamous cell carcinoma that arises from the tongue. "For instance, miR-2392, together with Argonaute 2 (Ago2), has been reported to partially inhibit mtDNA transcription in tongue squamous cell carcinoma cells (TSCC), resulting in down-regulation of oxidative phosphorylation and up-regulation of glycolysis." (PMID 34975760, 2021).